ANGPTL4 (angiopoietin like 4)
Diseases named in the same sentence as ANGPTL4 in open-access papers (continued):
Sharing a sentence is not in itself a finding about the gene and the disease.
type 2 diabetes (continued). "Taken together, oral lipid tolerance tests should be investigated in obese and type 2 diabetic patients to compare the dynamics of Angptl3 and Angptl4 after lipid uptake." (PMID 34951653, 2022). "Blood glucose concentrations were inversely correlated with ANGPTL4, and in patients with type 2 diabetes, their blood glucose concentrations were higher, but ANGPTL4 concentrations were lower." (PMID 35874833, 2022). "Overall, these data make it difficult to assign a role for aberrant ANGPTL4 regulation in post-prandial hypertriglyceridemia in type 2 diabetes." (PMID 32504883, 2020). "Mean baseline ANGPTL3/8 and ANGPTL4/8 levels in these type 2 diabetes patients were 19 and 45 ng/ml, respectively." (PMID 32487544, 2020). "Previous study demonstrated that patients with type 2 diabetes have lower plasma ANGPTL4 concentrations than the healthy group." (PMID 30049845, 2018). "This suggests that reducing ANGPTL4 could offer therapeutic advantages to a wider group of patients with dyslipidaemia and Type 2 diabetes." (PMID 38895109, 2024). "Collectively, the data suggest that ANGPTL4 ASO may not only be useful for treating hypertriglyceridemia but could also be valuable in the therapeutic management of type 2 diabetes." (PMID 35667416, 2022). "Given that the primary analysis suggested that ANGPTL4 and ANGPTL8 PTVs may reduce triglyceride levels, we tested these PTVs’ impact on type 2 diabetes (T2D), coronary artery disease (CAD) risk in 218,792 individuals from the FinnGen Study." (PMID 33909604, 2021). "It has also been reported that serum ANGPTL4 is lower in subjects with type 2 diabetes." (PMID 31164103, 2019). "In type 2 diabetes, circulating ANGPTL4 is increased to protect HDLs from hydrolysis." (PMID 30049845, 2018). "Interestingly, serum ANGPTL4 levels are inversely correlated with plasma glucose concentrations and the serum levels are significantly lower in type 2 diabetic patients than healthy subjects." (PMID 22471940, 2012). "However, data suggests that ANGPTL-4 has different effects depending on whether test subjects are obese, have Type 2 diabetes, or have overexpression of ANGPTL-4." (PMID 32785136, 2020). "In patients with type 2 diabetes, the elevated serum triglyceride levels negatively correlate with circulating LPL levels, and positively with circulating APOC1, APOC3, ANGPTL3, ANGPTL4 and ANGPTL8 levels." (PMID 37448184, 2023). "In young and middle-aged adults, serum levels of ANGPTL4 were inversely related to fasting glucose, and HOMA-IR levels were lower in patients with type 2 diabetes than healthy adults." (PMID 32878157, 2020). "In humans, ANGPTL4 levels are inversely correlated with glycemia and HOMA-IR, while in patients with type 2 diabetes, plasma levels of ANGPTL4 are significantly lower than in healthy subjects." (PMID 31170218, 2019). "Genetically lowering circulating ANGPTL4 levels reduced the odds of coronary artery disease (CAD) [odds ratio, 0.57 per s.d. protein (95% CI 0.47–0.70)] and Type 2 diabetes (T2D) [odds ratio, 0.73 per s.d. protein (95% CI 0.57–0.94)]." (PMID 38895109, 2024). "Angiopoietin-like protein 4 (ANGPTL4) regulates lipid partitioning by inhibiting circulating and tissue lipoprotein lipase (LPL); ANGPTL4 loss-of-function variants improve insulin sensitivity and reduce type 2 diabetes (T2D) risk with mechanisms partially unknown." (PMID 33003532, 2020).
metabolic syndrome (51 papers, 2008 to 2025). A cluster of metabolic risk factors for CARDIOVASCULAR DISEASES and TYPE 2 DIABETES MELLITUS. "ANGPTL4 is a highly anticipated pharmacological target for improving dyslipidemia and reducing cardiovascular risk." (PMID 38431115, 2024). "Given that ANGPTL4 is a highly anticipated pharmacological target for improving dyslipidemia and reducing cardiovascular risk, it is important to address these questions." (PMID 38431115, 2024). "To investigate the relationship of serum ANGPTL4 in SUA-associated dyslipidemia, we analyzed the correlation between ANGPTL4 and TRL-C in the high SUA group and the low SUA group after adjusting the confounders (sex, gender, and BMI), respectively." (PMID 35711366, 2022). "The human Angptl4 E40K mutation can deactivate Angptl4, thereby reducing triglycerides, increasing high-density lipoprotein cholesterol, and reducing dyslipidemia and arteriosclerosis, as well as the incidence of cardiovascular disease." (PMID 36285165, 2022). "Our findings link the interaction between dyslipidemia and cancer metastasis and provide new insight into coincident ANGPTL4 and NOX4 expression as a potential diagnostic biomarker and therapeutic target for CRC therapy." (PMID 32641980, 2020). "The crucial role of ANGPTL4 in governing plasma lipid levels in mice and humans has made ANGPTL4 an attractive therapeutic target for correcting dyslipidemia and associated cardiovascular disorders." (PMID 32504883, 2020). "ANGPTL4 was independently and negatively associated with carotid artery sclerosis measured by 3-T magnetic resonance imaging in subjects with metabolic syndrome and low-grade systemic inflammation." (PMID 30323852, 2018). "ANGPTL4 also seems to play a relevant role in type 2 diabetes mellitus and in the metabolic syndrome, both associated with dyslipidemia." (PMID 24478758, 2014). "Additionally, ANGPTL4 mediates tumor proliferation and metastasis through metabolic pathways in both dyslipidemia-associated CRC and F. nucleatum-related CRC." (PMID 38643448, 2024). "Also, this interaction between ANGPTL4 and SUA-related lipid disturbance creates the possibility for ANGPTL4-targeted therapies to impart a significant benefit in hyperuricemia-associated dyslipidemia." (PMID 35711366, 2022). "Concerning the discordant results, we still need to conduct more large-scale clinical trials and in-depth basic experiments to further elucidate the essential role of ANGPTL4 in modulating the risk and the development of dyslipidemia in patients with hypothyroidism." (PMID 34784265, 2022). "They revealed that knockdown of ANGPTL4, NOX 4, and other parameters dramatically inhibited circulating tumor cell extravasation and metastatic seeding of tumor cells in the lungs, indicating that the ANGPTL4/NOX 4 axis is critical for dyslipidemia-associated tumor metastasis." (PMID 34445141, 2021). "Thus, further investigation is necessary to reveal which form of ANGPTL4 is associated with dyslipidemia." (PMID 29538435, 2018). "Thus, we hypothesize that functional polymorphisms in the ANGPTL4 gene are involved in the regulation of dyslipidemia in OSA." (PMID 38574398, 2024). "Interestingly, accumulating studies have found that circulating ANGPTL4 is greatly increased in patients with metabolic syndrome or diabetes and is highly associated with metabolic traits, which is similar to the association of SUA with risk of metabolic syndrome." (PMID 35711366, 2022). "Therefore, FIH-1, HIF-1, and Angptl4 may play important roles in the treatment of dyslipidemia caused by CIH." (PMID 36285165, 2022). "Similar findings have been reported in other populations, and few associations were found between ANGPTL3, ANGPTL4, or ANGPLT8 levels with features of metabolic syndrome." (PMID 38879166, 2024).
metabolic syndrome (continued). "Future studies should continue to explore the specific mechanisms of ANGPTL4 in dyslipidemia-induced renal damage and evaluate its potential as a novel biomarker for treating dyslipidemic kidney disease." (PMID 39840089, 2024). "The impact of ANGPTL4 T266M on dyslipidemia has been studied in metabolic diseases such as T2DM, but it does not significantly affect the development of prediabetic phenotypes in the white population." (PMID 38574398, 2024). "Both ANGPTL3 and ANGPTL4 have been utilized as novel therapeutic targets for the treatment of dyslipidemia." (PMID 38160757, 2023). "In CIH disease models, HIF-1 promotes Angptl4-mediated dyslipidemia and upregulates the expression of Angptl4, which, in turn, inhibits LPL activity and catalytic function, resulting in hyperlipidemia." (PMID 36285165, 2022). "ANGPTL4 has indicated the potential to treat cardiovascular disease, hyperlipidemia, diabetic eye disease, and metabolic syndrome." (PMID 36553482, 2022). "This is complemented by our previously cell experiment which proved DLT had positive effects in improving dyslipidemia and arteriosclerosis by inhibiting Angptl4 protein levels through HIF-1α-Angptl4 mRNA signaling pathway." (PMID 36285165, 2022). "Recent studies have reported that circulating ANGPTL4 is strongly related to lipid and multiple features of the metabolic syndrome." (PMID 35711366, 2022). "The monoclonal antibody injected with human Angptl4 in mice and monkeys can also inhibit triglyceride levels and improve atherosclerosis and dyslipidemia." (PMID 36285165, 2022). "Considering the role of inflammation status in dyslipidemia and serum ANGPTL4 level, we also assessed the relationship between the serum ANGPTL4 and hs-CRP, an established marker of inflammation." (PMID 35711366, 2022). "These beneficial effects of ANGPTL4 are much more prominent, despite the accompanying lipogenesis with dyslipidemia and hepatic steatosis." (PMID 36292250, 2022). "Both HIF-1 and Angptl4 play important roles in the promotion of dyslipidemia and arteriosclerosis in CIH." (PMID 36285165, 2022). "As a tissue-specific proangiogenic or antiangiogenic agent, angiopoietin-like 4 (ANGPTL4) has recently gained attention in many diseases, such as metabolic syndrome, cardiovascular disease and cancer." (PMID 33726754, 2021). "A study of 1,770 diabetic Caucasian individuals displaying metabolic syndrome revealed that serum ANGPTL4 levels were positively correlated with TG levels, while there was a significantly negative correlation with LDL-C and HDL-C." (PMID 32280690, 2020). "General contributions of ANGPTL4 to dyslipidemia and coronary artery disease (CAD) has also been demonstrated." (PMID 30049845, 2018). "Although its role in the context of metabolic diseases is still elusive, ANGPTL4 plasma levels have been reported to be significantly higher in patients with metabolic syndrome and were predictive for future cardiovascular events." (PMID 27187453, 2016). "Further research will be required to more accurately elucidate the function of Angptl4, but also of Il18, Fgf15, Mif and Igfbp3 in the small intestine and their possible role in the etiology of the metabolic syndrome." (PMID 18457598, 2008). "Research on the mechanisms of ANGPTL4 in dyslipidemia-induced renal damage remains limited." (PMID 39840089, 2024). "The effect of ANGPTL4 on dyslipidemia was transient and attenuated at the later stage." (PMID 38574398, 2024). "The underlying mechanism related to the effects of DLT on CIH-induced dyslipidemia may be associated with the upregulation of FIH-1 and downregulation of HIF-1 and Angptl4." (PMID 36285165, 2022). "Therefore, research on the treatment of dyslipidemia and atherosclerosis with angiopoietin-like 3 and Angptl4-related antibodies has also emerged, although such treatment has not yet been widely used in clinical practice." (PMID 36285165, 2022).
metabolic syndrome (continued). "Notably, the functions of ANGPTL4 in modulating dyslipidemia were discordant according to the results provided by diverse results." (PMID 34784265, 2022). "Since the p.Glu15Lys ANGPTL4 allele lowers susceptibility to ASCVD by reducing repression of LPL activity, ANGPTL4 might seem to be a promising target for therapeutic management of dyslipidemia." (PMID 34336854, 2021). "Thus, this study provides a new understanding of how the dyslipidemia-induced ANGPTL4/NOX4 axis contributes to CRC metastasis." (PMID 32641980, 2020). "Taking into consideration the repression of adipocyte ANGPTL4 mRNA by insulin, the upregulation of ANGPTL4 in insulin resistance may contribute to the postprandial dyslipidemia in insulin-resistant individuals via inhibition of LPL." (PMID 32504883, 2020). "Abundant evidences opened the way to speculate a potential synergic role of PPARs and ANGPTL4 as key players in the cross talk between metabolic syndromes and cancer." (PMID 28182091, 2017). "ANGPTL4 concentration has a positive correlation with TG in patients with the metabolic syndrome." (PMID 27004807, 2016). "Thus, Angptl4 provides a molecular link between proteinuria and hypertriglyceridemia and could explain the presence of dyslipidemia in patients with near-normal serum albumin levels (as in the present study)." (PMID 38720111, 2024). "However, the contributions of ANGPTL4 genetic variants to dyslipidemia in OSA are not well understood." (PMID 38574398, 2024). "Dyslipidemia was not an independent factor associated with ANGPTL4, CRP, and ESR." (PMID 36790644, 2023). "Indeed, we could not rule out the possibility that some key parameters, such as glucose, insulin, and glucagon, may attenuate the relationship between the ANGPTL4 and SUA-associated dyslipidemia." (PMID 35711366, 2022). "Experimental and clinical studies have revealed several mechanisms through which high serum angiopoietin-like protein 4 (ANGPTL4) level exerts deleterious effects on lipid metabolism, but the role of ANGPTL4 in SUA-associated dyslipidemia has not been well studied, so far." (PMID 35711366, 2022). "However, the increase in serum ANGPTL4 may be related to insulin resistance in patients with metabolic syndrome compared to normal patients." (PMID 33807959, 2021). "In kidney diseases, the expression and function of ANGPTL4 are particularly significant, especially in conditions such as nephrotic syndrome, DKD, lupus nephritis (LN), renal cell carcinoma (RCC), dyslipidemia-induced renal damage, and AKI." (PMID 39840089, 2024). "As the main regulator of Angptl4, HIF-1 plays a role in promoting arteriosclerosis and dyslipidemia by upregulating Angptl4, inhibiting the expression of LPL, and increasing triglycerides and lipids in CIH-induced lipid metabolism and arteriosclerosis." (PMID 36285165, 2022). "Additional novel findings in our study are the inverse correlations of ANGPTL3/8 and ANGPTL4/8 with HDL, and the direct correlations of both complexes with all other metabolic syndrome markers." (PMID 32487544, 2020). "In human serum, ANGPTL3/8 and ANGPTL4/8 complexes both increased postprandially, correlated negatively with HDL, and correlated positively with all other metabolic syndrome markers." (PMID 32487544, 2020). "Future research should investigate the feasibility of using ANGPTL3, ANGPTL4, and ANGPTL8 as biomarkers in DR and assess whether ANGPTL3-targeted therapies can improve disease progression in DR while managing dyslipidemia." (PMID 40559376, 2025). "Yet, the functions of ANGPTL4 and ACACA in dyslipidemia of obstructive sleep apnea (OSA) remain unclear." (PMID 38574398, 2024). "Therefore, we concluded that CIH aggravates dyslipidemia, but DLT alleviated this interference and exerted a similar effect as that of Angptl4-ab." (PMID 36285165, 2022).
metabolic syndrome (continued). "A multivariable analysis was performed to assess whether the ANGPTL4, ApoC3, and LPL axis was altered in RA and to study its relationship with RA dyslipidemia and subclinical carotid atherosclerosis." (PMID 35488290, 2022). "Furthermore, inactivating variants in ANGPTL4 are associated with reduced risk of coronary artery disease in humans, suggesting that ANGPTL4 and related LPL modulators may be targets for modification of dyslipidemia-related atherosclerotic cardiovascular disease." (PMID 29899519, 2018). "Moreover, IH-induced dyslipidemia can also be related to decreased lipoprotein clearance due to the inhibition of lipoprotein lipase (LPL) mediated by HIF-1 and Angiopoietin-Like 4 (Angptl4)." (PMID 25834642, 2015). "However, the regulation of ANGPTL4 in metabolic syndrome has not yet been extensively studied." (PMID 35711366, 2022). "In a cross-sectional study including 1770 Caucasian subjects, plasma ANGPTL3 and ANGPTL4 concentrations showed different relationships with plasma lipids; ANGPTL3 was positively associated with LDL cholesterol and HDL cholesterol and not with metabolic syndrome traits including TGs." (PMID 26739706, 2016). "Previous studies have shown that CIH can induce dyslipidemia and atherosclerosis in ApoE−/− mice by inhibiting the expression and activity of LPL and affecting the expression of Angptl4, a potential inhibitor of LPL in adipose tissue but not in heart tissue." (PMID 36285165, 2022).